IL1B (interleukin 1 beta)
Diseases named in the same sentence as IL1B in open-access papers (continued):
Sharing a sentence is not in itself a finding about the gene and the disease.
infection (continued). "IL1β has both pro and anti-inflammatory behavior, the increase in fold change of IL1β is in synchrony with IL10 and TGFβ which shows its predominant anti-inflammatory action in establishing infection during early stage." (PMID 35011356, 2021). "In this study, the levels of pro-inflammatory cytokines, including IL-1β, IL-6, TNF-α and IFN-γ, were elevated after infection, suggesting the innate immunity was activated by PRV." (PMID 34275451, 2021). "NF-κB is believed to be a major regulator of inflammation, and IL-1β, IL-6 and TNF-α are rapidly released in response to tissue injury or infection." (PMID 35096806, 2021). "The observed increased expression of IL-1β, IL-6, and IP-10 in DSS and DHF can be attributed to DENV E triggered cytokines, since majority of our samples are from primary infection." (PMID 34447698, 2021). "The mRNA level of IL-1β, IL-8, TNF-α, and IL-2 was down-regulated (<1-fold) in the early stages of infection." (PMID 34603235, 2021). "Administration of the inhibitor significantly prolonged survival of the animals and reduced the levels of circulating IL-1β and TNF-α and partly IL-6 at 20 hours after infection." (PMID 34236052, 2021). "Along these lines, upon infection with WR-IRF3, we observed changes in mRNA levels of IL-1β, the transcription of which is mediated by NF-κB." (PMID 34696416, 2021). "After 1 day of infection, the oral tissues of the gefitinib-treated mice contained significantly less CXCL1/KC, CCL20, IL-1α, IL-1β, IL-17A, and the host defense peptide S100A8 than control mice." (PMID 33471869, 2021). "In turn, a dramatic rise in IL-1β, IL-6, and TNF-α plasma concentrations was evident 20 hours after infection in i.v. iron-treated Fth-KO animals as compared with control and iron-administered WT animals and control-treated FthΔ/Δ mice." (PMID 34236052, 2021). "We observed that in vitro infection with GCRV induced the expression of IFN1, Mx2, IL-1β, and TNFα, indicating the initiation of antiviral response." (PMID 34068469, 2021). "Again, B. dorei-treatment significantly reduced the levels of IL-1β, IL-6, TNF-α, IL-10, MCP-1 and IP-10 in lung compared with PBS-treated infection mice at day 7 p.i., to a comparable degree relative to the oseltamivi treatment." (PMID 35154087, 2021). "Western blot analysis of the cell lysates combined with the cell culture supernatants (total) demonstrate that infection with SS−/− mutants led to decreased cleavage of GSDMD, CASP1, and IL-1β." (PMID 33441602, 2021). "Prior studies have found that expression of key inflammatory cytokines known to be increased during infection with SARS-CoV-1 (IL-1β) and SARS-CoV-2 (TNFα and IL-6) is increased during infection with MHV-A59 as well." (PMID 34479991, 2021). "As with infection with THP-1 macrophages, NuLi-1 cells infected with chronic P. aeruginosa isolates induced less IL-1β expression but more IL-6 expression, while the expression of TNF and IL-10 were undetectable (data not shown)." (PMID 33664232, 2021). "We found that CFT073 significantly increased the release of IL-1β from renal fibroblasts at MOI 1 and 10 after 6 h of infection compared to unstimulated cells." (PMID 34944029, 2021). "S.pn infection led to significantly increased inflammatory cytokine levels of TNF-α, IL-1β, and IL-6 in BALF (p < 0.01)." (PMID 35111047, 2021). "Pre-miR-2187 showed obviously inhibitory effect on NF-κB, IL-8, IL-1β, IRF3, and ISRE reporter genes during LPS or poly(I:C) infection." (PMID 33659012, 2021). "In THP1 cells, which are more resistant to infection than primary macrophages, foam cells displayed an increased production of inflammatory cytokines including TNF-α, IL-1β, and an increased IL-1β/IL-10 ratio, compared with macrophages." (PMID 34975863, 2021).
infection (continued). "Suggesting low systemic response, the blood of mice trained 9 weeks contained lower levels of a broad range of cytokines (IL-1β, IL-6, IL-10, IL-12p40, IL-17A, IL-18, IFNγ, TNF, CCL2 and CXCL5) 2 days after infection with L. monocytogenes." (PMID 34603295, 2021). "L-Kyn reduced the number of TNF-α+ and IL-1β+ CD11c+ cells at both infection periods but increased the number of IL-12 and TGF-β expressing CD11c+ cells by 96 hours of infection." (PMID 33936043, 2021). "The results of our study demonstrated that IL-1β/IL-18 levels were significantly elevated in the culture supernatants of macrophages infected with E.coli HPI, with higher levels detected following infection with the strain carrying the irp2 gene." (PMID 33678162, 2021). "Following infection, complement anaphylatoxins stimulate macrophages to produce TNF-α, IL‐1β, IL‐6, and IL‐8; these mediators promote vascular dysfunction, fibrinolysis, and microvascular thrombosis formation." (PMID 34276659, 2021). "Despite some variation between individual mice, BALF samples from LVS- and fpt mutant-infected mice showed significantly elevated levels of IFN-γ, TNF-α, IL-1β, IL-12p70, IL-10, IL-2, and KC/GRO compared to mock infection." (PMID 34202420, 2021). "Eight hours after infection with CVB3, we observe robust release of active IL-1β into the culture supernatant when cells were transfected with WT NLRP1 but not the uncleavable mutant NLRP1." (PMID 33410748, 2021). "Proinflammatory cytokines, such as IL-6, IL-1β, and TNF-α, play an essential role in infection-induced inflammatory responses." (PMID 34829902, 2021). "The production of CXCL1, IL-1β, TNF, and IL-6 was decreased in the lungs of Trem1−/- mice at early stages on the infection (2 dpi)." (PMID 33525982, 2021). "In the present study, the mRNA expression of inflammatory cytokines (IL-1β, IL-6, TNF-α) in the trachea and lung of group IV was lower compared with the expression levels of other groups from day 1 to 7 post-infection." (PMID 34988139, 2021). "The gene expressions of IL-1β and IFN-γ were significantly downregulated along with upregulation of NF-κB1 gene expression in G3 compared to G1 on the 7th and 14th day of infection." (PMID 35071376, 2021). "We used three different inflammatory stimuli, such as LPS from P. aeruginosa, mimicking the infection, and IL-1β/H2O2 and IL-1β/TNF-α, resembling the inflammatory milieu." (PMID 34440900, 2021). "The infection dose of MOI = 1, which secreted the highest levels of IL-1β p17, was selected for the different inoculation time assays." (PMID 34869071, 2021). "In control animals, we noted a significant increase in proinflammatory cytokines (IL-1α, IL-1β, IL-6, and TNF-α), and chemokines (RANTES/CCL5 and CXCL1) coupled with the surge of G-CSF in response to infection." (PMID 33514747, 2021). "S.pn infection led to significantly increased inflammatory cytokine levels of TNF-α, IL-1β, and IL-6 in BALF (p < 0.01), while QFY treatment of infected mice led to significantly decreased BALF levels of these cytokines." (PMID 34950611, 2021). "In sum, our data illustrate a critical role for CDI-induced IL-1β in upregulating neutrophil CXCR2 and their subsequent trafficking to the site of infection." (PMID 33718269, 2021). "The expression levels of IFN-α at 7 dpi and IL-1β and TNF-α at 5 dpi were also significantly higher (P < 0.05) in the IBV+H9N2 group than in the single-infection IBV and H9N2 groups." (PMID 35211536, 2021). "(A–C) Serum levels of inflammatory cytokines IL-1β (A), TNFα (B), and IL-6 (C) of young (6 months old) and old (24 months old) infected mice on day 8 post (PFU 7e2) infection." (PMID 34151773, 2021). "IL-1β secretion and mRNA transcription with positive control (LPS + Nigericin) and FMDV infection increased at different hours post-infection (hpi) or multiplicities of infection (MOIs) compared with the findings under the control conditions." (PMID 35062226, 2021).
infection (continued). "When infection, injury, or inflammation increases in severity, polarization initially adopts the M1 conformation, leading to a systemic influx of TNF-α, IL1β, IL-12, and IL-23 to reconcile a homeostatic state." (PMID 34831416, 2021). "The infection of RAW264.7 cells with RSV led to an increased expression of iNOS and IL-1β, as well as the decreased expression of Arg-1." (PMID 34384038, 2021). "We found upregulation in expression of the proinflammatory cytokines IL-1β, IL-6, TNF-α, and IL-12p35 as well as the chemokine CXCLi1 in chMoDCs treated with S. Typhimurium during the early phase of infection (6 h)." (PMID 34446765, 2021). "Increases in IL-15, IL-1β, IL-6, and TNF-α levels were slightly more delayed in the CSF, beginning closer to day 6 post-infection." (PMID 34001896, 2021). "Infection was accompanied by progressive upregulation of proinflammatory cytokines such as IL6, IL1B and TNF, consistent with initiation of an NF-KB-dependent inflammatory response." (PMID 34876592, 2021). "In the CF mice, within 48-h of B. pseudohinzii inoculation, there is a significant spike in IL-1β (p = 0.010), IFN-γ (p = 0.032), IL-6 (p = 0.019), and TNF-α (p = 0.040) serum levels, well beyond the infection naïve controls." (PMID 34475490, 2021). "Higher mRNA levels of inflammatory cytokines IL-1β, IL-6, IL-8, and TNF-α were observed during early symptomatic infection (JM-1) compared to healthy controls." (PMID 34669281, 2021). "The concentration of selected cytokines and chemokines in milk throughout the course of infection confirmed and extended the finding that MOK124 induced higher IL-1β and IL-8 concentrations in milk." (PMID 34740333, 2021). "Although this was the case, the noticeable decreases in IL-1β, IL-2, IL-4, IL-12, IL-13, RANTES, TNF-α, and GRO-α observed in patients with lethal SARS-CoV-2 infection suggest that lethal infection results in an exhausted immune response." (PMID 33472985, 2021). "The strong EPs 7630-induced inhibition of pro-inflammatory IL1B induction and upregulation of anti-inflammatory TNFAIP3 late post-infection encouraged us to have a closer look at the cytokine secretion profile of epithelial Calu-3 cells." (PMID 34759825, 2021). "Comparing to wide-type ZYAH72 infection group, the mRNA levels of pro-inflammatory cytokine tumor necrosis factor-α (TNF-α) and interleukin-1β (IL-1β) in the kidney and spleen of AHFGDS infection group were significantly reduced." (PMID 34063680, 2021). "In spite of equal microbicidal activity, it was observed that decitabine modulated the release of inflammatory cytokines, such as IL-1β, TNF-α, and IFN-γ, which showed a significant reduction after 7 days of infection when compared to the DMSO group." (PMID 33921194, 2021). "Infection with V. montpellierensis induced significant elevation of sFasL (P = 0.0250) and IL-1α (P = 0.0137), IL-1RA (P = 0.0095), TNF-α (P < 0.0001), IL-1β (P = 0.0470)." (PMID 34230496, 2021). "Previous studies have shown the importance of macrophage TLR2 activation for the secretion of IL-1β, IL-6, TNF-α, IFN-β during the infection with L.m." (PMID 34194428, 2021). "The pro-inflammatory molecules commonly increased during the infection with influenza virus are the IL-6, TNF-α, and IL-1β." (PMID 33917837, 2021). "The lung and trachea homogenates from all animals had detectable cytokines (IL-6, IL-1α, IL-1β, TNFα and TGFβ) and chemokine (MCP-1) at Day 7 post-infection." (PMID 34452519, 2021). "Compared with the normal control group, infection by ETEC K88 significantly increased serum TNF-α, IL-6, IL-1β, IFN-γ, VIP, sIgA and histamine levels, as well as the β-hexosaminidase, tryptase and MPO activities." (PMID 34899686, 2021). "IL-1β is a proinflammatory cytokine in the toll-like receptor signaling and NLRP3 inflammasome pathways, which are crucial for host defense responses to infection." (PMID 33469074, 2021).
infection (continued). "We found the expressions of mRNA expression of caspase-1, GSDMD, caspase-3, MLKL, RIPK3, NLRP3, IL-1β and IL-18 and of proteins cleaved caspase-1, GSDMD, cleaved caspase-3 and pMIKL in the macrophages of the three infection groups to be upregulated (P<0.05)." (PMID 34513732, 2021). "IL-1β and TNF-α are typical proinflammatory cytokines that are induced at the early stage of pathogen infection to enhance macrophage survival and the bactericidal activity of leukocytes by increasing ROS production during phagocytosis." (PMID 34946096, 2021). "Expression of CRP is induced by IL-6 and other cytokines (IL-1β, TNF) via NF-κB and other transcription factors as part of the acute-phase response or during inflammatory conditions and infections." (PMID 34925360, 2021). "Myeloid KLF4 KO mice showed reduced levels of TNF-α, KC and IL-1β and increased levels of IL-10 in BALF and plasma after infection with S. pneumoniae." (PMID 34589087, 2021). "The lung homogenates from Nlrp3−/− mice showed significantly higher levels of IL-1β, IL-6, IL-10, IL-12p70, G-CSF, GM-CSF, TNF-α, and RANTES than the wild-type mice on day 3 post-infection." (PMID 34690967, 2021). "Metformin treated 5637 cells increased mRNA expression of the proinflammatory cytokines IL1B and CXCL-8 upon infection." (PMID 34584119, 2021). "The IL-1β and IL-18 content in the control group was significantly lower than those in the HPI infection groups at 6 and 9 h post-infection (P < 0.01)." (PMID 33678162, 2021). "Under inflammatory conditions, there was an increased activation of IL-1β, IL-6, IL-8, TNF-α in MDCK cells following infection with C. jejuni RC039, S. enterica and C. perfringens." (PMID 34099034, 2021). "The polymicrobial infection with four BVAB resulted in a mixed profile and additional induction of IL-1β, a key cytokine consistently elevated among women with BV69,70." (PMID 34903740, 2021). "We observed a significant increase in the release of IL-1β in the supernatant of SFTSV infected cells, LPS, or LPS/Nigericin-treated cells compared with mock-infected cells on 48 h after infection." (PMID 33708197, 2021). "Next, we measured the expression of proinflammatory cytokines/mediators (IL-1β, TNF-α, IL-6 and iNOS) in brain lysates (cortex and hippocampus) and serum at 24 h post-infection by RT-PCR and ELISA, respectively." (PMID 34727939, 2021). "In this study, inflammasome pathway analysis showed that infection with virulent strains of T. cruzi leads to high increase in the expression of NLRP3, caspase-1 and IL-1β in the myocardium." (PMID 34336720, 2021). "Next, we defined proinflammatory macrophages as cells expressing high levels of CCL2 and CCL3, chemokines involved in recruitment of adaptive and innate cells to sites of infection, and which were also characterized by the expression IL6, IL1B, and TNF." (PMID 33622974, 2021). "BMDMs from these Ifnar−/− mice also exhibited increased expression of Il1b, Tnf, and Il6 with MHV-A59 infection compared to uninfected Ifnar+/+ controls." (PMID 34479991, 2021). "To determine the contribution of ASC-dependent inflammasomes to IL-1β and IL-18 production in HSE, we assayed mice early after infection and prior to mortality (days 1 and 3)." (PMID 33524073, 2021). "Aim2 is a dsDNA sensor that upon recognition induces the formation of an inflammasome complex releasing IL1β and IL18 from the cell as a defense mechanism to control infection." (PMID 34047695, 2021). "Acute phase cytokines that appear minutes to hours after infection include tumour necrosis factor (TNF) and interleukin 1 beta (IL-1β) as well as interleukin 8 (IL-8) and monocyte chemoattractant protein-1 (MCP-1), which are chemotactic cytokines." (PMID 34960696, 2021). "Another previous study showed that the consequences of early life stress-induced infection altered cytokine production, such as IL-6, TNF-α, or IL-1β, and changed behaviors in later life." (PMID 33441182, 2021).
infection (continued). "Proinflammatory cytokines, such as IL-1β, IL-6, IFNα/β, and TNFα, produced upon TMEV infection via TLR-mediated signals, further upregulate the production of chemokines." (PMID 34067536, 2021). "The levels of cytokines (IL-6, TNF-α, IL-1β) and chemokine (CCL2) were upregulated in response to the B.1.1.7 and B.1.351 infection in the lungs." (PMID 35062231, 2021). "Nlrp3−/− mice infected with F. tularensis LVS had significantly higher levels of IL-1β, IL-6, IL-12p40, G-CSF, GM-CSF, TNF-α, and RANTES as compared to the wild-type mice on day 3 post-infection." (PMID 34690967, 2021). "Mabs infection robustly increased the production of proinflammatory cytokines including TNF-α, IL-6, and IL-1β in BMDMs at 18 hpi." (PMID 34447358, 2021). "The infection of rat coronavirus (RCoV) to the AT1 cells will induce more expression of IL-1α and IL-1β, which will further send more signals through the IL-1 receptor (IL-1R) of the cells not infected in order to induce more CXC chemokine release." (PMID 34367545, 2021). "In the meantime, the inflammasome effectors including caspase-1, IL-1β, and GSDMD largely increased at infection; whereas IL-18 decreased during infection." (PMID 34161342, 2021). "We observed that infected WT mice exhibit a mixed response of Th1 and Th2 already in the initial stage of infection (3dpi), represented by an increase in IFN- γ, IL-1β, IL-33, IL-13 and IL-5." (PMID 34324507, 2021). "HPI+/HPI−-infection was accompanied by upregulated expression levels of NLRP3, ASC, caspase-1, IL-1β, IL-18 and GSDMD, with significantly higher levels detected in the HPI+ group compared to those in the HPI− group (P < 0.01 or P < 0.05)." (PMID 33678162, 2021). "Infection of human monocytes with K. kingae performed at MOIs of 1 and 10 elicited the secretion of IL-6, TNF-α, and IL-1β at 24 h post-infection in an inoculum-dependent manner." (PMID 34925328, 2021). "In the present study, C. perfringens challenge upregulated jejunal IL-1β and TGF-β4 expression, which was downregulated by B. coagulans and L. fermentum, respectively, soon after the infection (day 21)." (PMID 34136557, 2021). "What is more, we found out that the levels of IL1β, IL8, RANTES (CCL5), MCP-2, and IGF1 were significant higher in early stage of infection." (PMID 35095832, 2021). "In addition, exosomes which targeting NLRP3 and its downstream IL-1β offer an anti-inflammation therapy method without increasing the risk of infection, as anti-IL-1β therapy might directly induce immunosuppression." (PMID 35047512, 2021). "This is an expected reaction upon infection and responses with several of these chemokines and cytokines have also been monitored upon Eimeria infection in chickens, e.g. CCL4, IL-8, IL-1β and CSF3." (PMID 33536090, 2021). "The classically activated M1 macrophages secrete proinflammatory cytokines, such as IL-1β, IL-6, IL-12, IL-23, and TNF-α, in response to stress and infection." (PMID 34360840, 2021). "In contrast, bacterial burden was most affected in caspase-1 KO mice at day 14 post-infection, in agreement with caspase-1 activity occurring subsequent to TLR2 signaling to maximize IL-1β production." (PMID 32290861, 2020). "We found that infection of colonoids with EAEC also induces the secretion of pro-inflammatory cytokines including IL-8, IP-10, MCP-1, IL-12 and IL-1B." (PMID 32601325, 2020). "The lung homogenates of WT and AhR−/− mice were collected after 96 h, 2 and 10 weeks of infection and used to evaluate the presence of cytokines (IL-12, TNF-α, IL-1β, IL-6, IL-23, IL-2, IFN-γ, IL-4, IL-17, IL-22, TGF-β, IL-10, IL-27, and IL-35)." (PMID 32647342, 2020). "IL-1β (P < 0.05) and CXCL10 (P < 0.05) were both significantly but modestly reduced in the KO animals on day 4 after infection." (PMID 32611756, 2020). "Highly expression of the inflammatory factors from IL-1 family such as IL-1α, IL1-β, and IL-RN was found in C13-PD-L1+ (CD274+) neutrophils at the early stage of infection (day 1 p.i.)." (PMID 32101596, 2020).